ALB (albumin)
Diseases named in the same sentence as ALB in open-access papers (continued):
Sharing a sentence is not in itself a finding about the gene and the disease.
diabetes (continued). "Urine albumin creatinine ratio, UACR, is positively associated with all-cause mortality, cardiovascular disease and diabetes in observational studies." (PMID 24675825, 2014). "Other potential causes were previous peritonitis, inadequate dialysis, low serum albumin, transfer set soaking with antiseptics, patient history of diabetes, dressing technique, and existence of dry abdomen period." (PMID 24997794, 2014). "Although our patient has been diagnosed to have type 1 diabetes mellitus her renal function tests were normal including urine albumin creatinine ratio, serum creatinine and estimated glomerular filtration rate." (PMID 25518745, 2014). "Covariates included age, gender, race, prior stroke, diabetes mellitus, dialysis modality, body mass index, serum albumin and other co-morbid conditions from the Medical Evidence Form." (PMID 24571546, 2014). "Animal studies demonstrated that the renal BMP7 protected against DN, and the BMP7 partially reversed kidney hypertrophy induced by diabetes, urine albumin excretion, restoring GFR, as well as glomerular histology toward normal." (PMID 25359423, 2014). "The risk of peritonitis was decreased by 57% in patients treated with oral active vitamin D (HR 0.43; 95% CI 0.28–0.64; adjusted for albumin, hemoglobin, age, renal disease, peripheral vascular disease, diabetes, center, and year of start of PD)." (PMID 23844107, 2013). "Patients with T1DM were 13.3 ± 3.9 years old with the duration of diabetes of 9.7 ± 3.6 years, mean arterial blood pressure of 86.0 ± 8.0 mmHg, serum levels of HbA1c 8.5 ± 1.9%, and albumin excretion rate of 24 ± 19 mg/24 h." (PMID 24222720, 2013). "The process of albumin glycation becomes very important especially in the case of diabetes where it can exert many adverse effects." (PMID 24250587, 2013). "In this study, SBP, CRP, lower serum albumin, uric acid, GGT and diabetes were significantly associated with albuminuria in the Aboriginal population." (PMID 23947772, 2013). "The presence of volume overload was associated with older age, diabetes, prior CVD, hypertension, higher inflammatory markers, and lower aldosterone, albumin, calcium, phosphate, and hemoglobin levels." (PMID 23469009, 2013). "Albumin exists in both reduced and oxidized forms in systemic circulation and the reduced form of the human serum albumin has been shown to be lower in patients with hepatic disorders, diabetes, and renal diseases." (PMID 26317017, 2013). "In an effort to improve diabetes management, national Clinical Practice Guidelines for general practice specify the requirements for testing of blood lipids, HbA1c, and urinary albumin." (PMID 23497486, 2013). "BMD of total spine and hip was positively correlated with BMI and negatively correlated with age, duration of diabetes, creatinine, and 24 h urinary albumin." (PMID 23401682, 2013). "Similar results were found from the Dallas Heart Study using urinary excretion of sodium-to-potassium ratio after adjustments for age, gender, race, diabetes, BMI, total cholesterol, estimated glomerular filtration rate, and urine albumin/creatinine ratio." (PMID 24130700, 2013). "Correlation analysis revealed that the BMD of total spine (L1–L4) was positively correlated with duration of physical activity and BMI and was negatively correlated with age, duration of diabetes, creatinine, and 24 h urinary albumin (all P ≤ 0.029)." (PMID 23401682, 2013). "Microalbuminuria refers to a slight increase in secretion of albumin in urine, and is a sign of progression towards nephropathy in patients with diabetes." (PMID 23841037, 2013). "Binding of diazepam to human serum albumin can be influenced by hypertension and diabetes due to changes in hemodynamic properties or by drugs used for their treatment." (PMID 24134697, 2013). "Compared with group 2 patients, group 1 patients were older, had a higher incidence of diabetes mellitus (DM), and had lower serum albumin levels and nPCR." (PMID 23372806, 2013).
diabetes (continued). "The detection of urinary nephrin from type 2 diabetic patients determined to be normoalbuminuric also showed that urinary nephrin was a more sensitive marker of nephropathy in diabetes than the measure of urinary albumin." (PMID 24327929, 2013). "Covariates included baseline eGFR, age, gender, race, diabetes duration, blood pressure, hemoglobin A1c and urine albumin:creatinine ratio." (PMID 23773264, 2013). "Blood urea nitrogen, serum glycated hemoglobin and uric acid levels, and the severity of urine protein were the highest and serum albumin was the lowest in patients with diabetes and fluid overload than others." (PMID 24349311, 2013). "The prevalence of NO, MI, and MA in subjects with diabetes was 51%, 21%, and 28%, respectively, giving a prevalence of nephropathy of 49%, as defined by an albumin to creatinine ratio above 30 mg/g." (PMID 24103534, 2013). "Whereas BMD of the total hip was positively correlated with BMI, waist-to-hip ratio, and serum calcium, it was negatively correlated with duration of diabetes, 24 h urinary albumin, FPG, TC, and LDL-C (P ≤ 0.031)." (PMID 23401682, 2013). "In model 2, in which albumin was excluded, D/Pcr, peritoneal Kt/V urea, and pulse pressure remained in the model with the additional inclusion of diabetes and increased serum CRP levels (Model 2)." (PMID 23418538, 2013). "The patients with diabetes had lower creatinine levels and higher estimated glomerular filtration rate (eGFR) and urinary albumin-creatinine ratio compared with the control group." (PMID 23866070, 2013). "Previous history of cardiopathy, peripheral vascular disease, diabetes, serum albumin and transferrin were independent predictors of future CV events." (PMID 24959538, 2013). "Binary logistic regression (BLR) showed that advanced age, female sex, and diabetes mellitus conferred the greatest hazard of a serum albumin <3.8 g/dl (p</=0.008) followed by nPCR, dialysis vintage, and ferritin (p < 0.05)." (PMID 24499139, 2013). "Univariate analysis identified the following factors as significantly associated with RFS for all cases (n=74): Presence of LC (P=0.017), HBeAg positivity (P<0.001), serum albumin ≥4.2 g/dl (P=0.003) and presence of diabetes mellitus (P=0.028)." (PMID 24179497, 2013). "Advancing age, longer vintage, female gender, diabetes mellitus, nPCR, serum phosphate and ferritin had significant correlation with albumin <3.8 g/dl (p < 0.05)." (PMID 24499139, 2013). "Of all of the liver function parameters in DK patients, the levels of GGT, total protein, albumin, globulin, and prealbumin were significantly lower than in patients with stable diabetes and control subjects (P < 0.001 and P < 0.05, resp)." (PMID 24282823, 2013). "Two hundred and fifty patients of type 2 diabetes mellitus were divided into two groups according to urinary albumin excretion rate (UAER): normoalbuminuria group (130 cases) and microalbuminuria group (120 cases)." (PMID 23573090, 2013). "In type 1 diabetic patients with diabetes duration ≥ 5 years, the screening for nephropathy should include an annual assessment of urine albumin excretion." (PMID 24165454, 2013). "We did not control for clinically relevant variables such as glycated haemoglobin levels, urinary albumin-to-creatinine ratio, systolic blood pressure, serum creatinine, diabetes complications, and antidepressants." (PMID 23343405, 2013). "In this high risk Aboriginal population, SBP, serum albumin (inverse association), uric acid, CRP, diabetes were significantly associated with albuminuria (p value for GGT was 0.054)." (PMID 23947772, 2013). "Here, we show that diabetes-induced increase in VEGF expression is associated with significant increases in ROS generation, increases in ICAM1 and abnormal accumulation of albumin outside of retinal vessels." (PMID 24358357, 2013). "CCI was a better predictor than models containing age, diabetes, cardiovascular disease, or albumin." (PMID 23626754, 2013).
diabetes (continued). "Trivedi and colleagues replaced FBS with 20% human albumin during the ASC expansion for clinical use to treat diabetes, whereas Tzouvelekis and colleagues used autologous platelet-rich plasma for the cell expansion to treat patients with pulmonary fibrosis." (PMID 23497764, 2013). "We should specify that the diagnosis of diabetic glomerulopathy in the NephroTest cohort was based on either renal biopsy or clinical data (diabetes, renal failure, high urinary albumin excretion, and/or other microvascular complications)." (PMID 24349134, 2013). "In the present study, the increase in urinary albumin concentration corresponding to hyperglycemia was more pronounced eight weeks following the induction of diabetes." (PMID 23476687, 2013). "We have excluded participants with self-reported kidney diseases,diabetes or cardiovascular diseases in the analyses to minimize the influence of diet change or medication use on blood pressure, urinary albumin excretion or renal function." (PMID 22802927, 2012). "One potential reason for our finding is that, in the undeveloped regions in our study, the patients were younger, there were fewer cases of diabetes, and baseline serum albumin levels were higher than in the developed regions." (PMID 23226378, 2012). "In univariate analysis, age, diabetes mellitus, previous history of cardiovascular disease, smoking, lipid-lowering therapy, serum albumin, iPTH, and hs-CRP concentrations were significantly associated with the presence of AoAC at baseline." (PMID 23144974, 2012). "Gaps in care exist for diabetes and kidney disease as 54.9% of patients with diabetes received recommended hemoglobin-A1c screenings, and only 55.8% received an albumin excretion test." (PMID 22970753, 2012). "In the PREVEND cohort study, the multivariable-adjusted ORs (95%CI) for the risk of diabetes were 1.22 (1.09–1.38), 1.29 (1.11–1.50), 1.16 (0.89–1.50) and 0.31 (0.87–1.05) per 100% increase of concentrations of GGT, ALT, AST and albumin, respectively." (PMID 23284703, 2012). "The residual tests indicate that most of the covariates satisfy the proportional hazards assumption with the exception of diabetes (p = 0.05), duration of dialysis (p = 0.05), systolic blood pressure (p <0.01), smoking (p = 0.03), and albumin (p <0.01)." (PMID 23025844, 2012). "After adjustment for age, sex, diabetes, dyslipidaemia, albumin and functional dependence, the presence of AF was significantly associated with mortality risk (RR 2.0, P = .011)." (PMID 22520618, 2012). "Increase in urinary albumin concentration corresponding to the hyperglycemia was observed in rats following diabetes induction." (PMID 21837246, 2012). "Supporting this, an increased FL residue content of albumin excreted in urine of patients with diabetes and microalbuminuria compared to patients with diabetes and normoalbuminuria has been previously observed." (PMID 22558190, 2012). "Diabetes was induced with streptozotocin and plasma glucose levels and albumin excretion rate (AER) were measured at predetermined times throughout the 23 week study period." (PMID 23028588, 2012). "In light of these reports, one can reasonably infer that measurement of glycated albumin provides a crucial piece of information to complement plasma glucose and HbA1c determination for appropriate diabetes monitoring and therapeutics." (PMID 22393405, 2012). "In the EPIC-NL case-cohort study, the multivariable-adjusted HRs (95%CI) for the risk of diabetes were 1.49 (1.37–1.61), 1.22 (1.09–1.37), 0.97 (0.81–1.17) and 0.34 (0.21–0.54) per doubling concentrations of GGT, ALT, AST and albumin, respectively." (PMID 23284703, 2012). "Independent biochemical predictors of cardiovascular and/or diabetes death included C‐reactive protein levels, urinary albumin/creatinine ratio, and C‐peptide levels." (PMID 23316320, 2012).
diabetes (continued). "Clinically, glycated albumin concentrations show a strong correlation with the development of serious diabetes complications including nephropathy and retinopathy." (PMID 22393405, 2012). "Given that age, diabetes and serum albumin have been recognized as the strongest predictors by most studies, these favorable individual factors in our study possibly offset the disadvantages of regional SES." (PMID 23226378, 2012). "The predictors most commonly included in the final prediction models were age, sex, body mass index, diabetes status, systolic blood pressure, serum creatinine, a measure of proteinuria, and serum albumin or total protein." (PMID 23185136, 2012). "In multivariate analysis, after adjusting for diabetes status, age, gender, HD vintage, Kt/Vurea, fetuin A, chemerin and albumin levels, only higher chemerin level had significant power to predict the diagnosis of central obesity (P = 0.02)." (PMID 22815691, 2012). "Glomerular filtration rate <45 ml/min/1.73 m2, age ≥ 61 years, cardiovascular disease (CVD), diabetes, C-reactive protein (CRP) ≥5 mg/L, haemoglobin ≤110 g/L, p-albumin ≤ 35 g/L and overweight were associated with impaired HRQoL." (PMID 22710013, 2012). "Patients with ABI < 0.9 tended to be older and have a higher prevalence of diabetes and hypertension, higher systolic blood pressure and pulse pressure, lower serum albumin level, higher UPCR, and a higher prevalence of calcium channel blocker usage." (PMID 22272169, 2012). "In conclusion, the present data clearly demonstrate that administration of APSAE reduces metabolic factors influencing diabetic nephropathy such as blood glucose, albumin, total protein creatinine and HbA1c in experimental diabetes." (PMID 25050253, 2012). "In the Baltimore Longitudinal Study of Ageing (1% with diabetes), both cross-sectional and longitudinal components of the four BP indices were examined in relation with urinary albumin excretion (UAE)." (PMID 22655101, 2012). "The additional presence of glucose in the urine (category 3 coloring, corresponding to 0.5% [g/dL]) indicated the onset of diabetes, whereas increased albumin levels in 24-hour urine samples suggested the presence of early renal damage." (PMID 23071636, 2012). "The Diabetes Atherosclerosis Intervention Study (DAIS) reported reduced progression of albumin excretion for fenofibrate treatment versus placebo." (PMID 22978715, 2012). "The risk factors most commonly included in these models were age, sex, body mass index, diabetes status, systolic blood pressure, serum creatinine, protein in the urine, and serum albumin or total protein." (PMID 23185136, 2012). "An inverse correlation was found between total serum bilirubin concentration and 24-hour urine albumin in all subjects and in subjects with diabetes (r = -0.228, p = 0.0001; r = -0.227, p = 0.0001)." (PMID 21708045, 2011). "Due emphasis should be given to clinical examination and urine albumin test to screen for chronic complications of diabetes which are highly cost effective in such resource constraint settings." (PMID 22185229, 2011). "A raised level of albumin in the urine is a typical indicator that the kidneys have been injured by diabetes." (PMID 21716679, 2011). "Plant flavonoids inhibited fructose-mediated glycation of albumin improving the symptoms of diabetes." (PMID 19622599, 2011). "The kidneys are enlarged in diabetes mellitus when they have microalbuminuria or overt levels of albumin excretion." (PMID 21716679, 2011). "In the context of diabetes, four of eight trials successfully increased timely monitoring of common targets such as HbA1c, blood lipids, blood pressure, urine albumin, and foot and eye health." (PMID 21824382, 2011). "BMI and albumin decreased with increasing age, while waist-hip ratio, systolic blood pressure, prevalence of diabetes, adiponectin, IL-6, and bilirubin increased with age." (PMID 21170382, 2010).
diabetes (continued). "Negative correlation was also seen between serum C peptide, and urine albumin, urine albumin creatinine ratio, HbA1C and duration of diabetes." (PMID 20535267, 2010). "The present study is aimed at correlating the serum C peptide level with that of renal clearance, urinary albumin excretion and duration of diabetes." (PMID 20535267, 2010). "The screening of Chronic Kidney Disease (CKD) in patients with diabetes is based on the Albumin excretion rate (AER, threshold: 30 mg/24 H) and the estimated Glomerular Filtration Rate (e-GFR, threshold: 60 mL/min/1.73 m2)." (PMID 20199663, 2010). "Negative correlation was also seen with serum C peptide vs urine albumin level (r = -0.059, P>0.05), vs. urine albumin creatinine ratio (r = -0.015, P>0.05), vs. HbA1C (r = -0.207, P>0.05) and vs. duration of diabetes (r = -0.171, P>0.05)." (PMID 20535267, 2010). "Factors significantly (p < 0.05) associated with poor overall survival were age at assessment, diabetes, serum albumin, peak VO2 max, shuttle walk distance, and predicted postoperative transfer factor." (PMID 21176210, 2010). "By design, the patients with diabetes had higher albumin excretion rates, as determined by a random urine for albumin to creatinine ratio." (PMID 20573241, 2010). "Minimization of variation between study arms in albumin excretion rate, gender, age, diabetes duration, HbA1c, total cholesterol and center location will be undertaken at randomization." (PMID 20017932, 2009). "At baseline, the mean diabetes duration was 22 years, 52% were male, 23% had kidney disease (urine albumin excretion over 300 mg/24 h or end-stage renal disease) and 8% had a history of macrovascular events." (PMID 19804653, 2009). "The groups were statistically significantly different in frequency of diagnosis of diabetes mellitus, incidence of head neck cancer, having radiotherapy treatment, and level of creatinine and albumin (P < 0.05)." (PMID 19785768, 2009). "After 5–10 years of type 1 diabetes mellitus, 40% of individuals begin to excrete small amounts of albumin in the urine (microalbuminuria)." (PMID 20142916, 2008). "Given that patients with toxic, ingestions, uremia, and those with ketoacidosis were excluded and that lactate and serum albumin are accounted for in the ALCAG equation, the amount of unmeasured anions in this cohort of critically ill patients is elevated." (PMID 19087326, 2008). "Those in the highest quintile were also more likely to smoke, to have hypertension and diabetes, to have a higher BMI, to have a higher urine albumin to creatinine ratio, and to have lower levels of both LDL and HDL." (PMID 18681974, 2008). "One week after induction of diabetes, the immunofluorescence assay, using anti-albumin antibody, disclosed staining only inside blood vessels in normal control eyes." (PMID 17293777, 2007). "Cox-regression analysis indicated that age, diabetes, albumin level, and hsCRP were independent factors predicting mortality." (PMID 18288267, 2007). "The results show that advanced age, serum hsCRP level, albumin level, and presenceof diabetes mellitus are independent predictors for mortality in chronichemodialysis patients." (PMID 18288267, 2007). "The rAAV-angiostatin injections led to sustained angiostatin gene expression in retina as confirmed by RT-PCR, and reduced extravascular albumin accumulation in STZ-induced diabetic retina." (PMID 17293777, 2007). "Type 2 patients with abnormal albumin excretion rate had significantly longer diabetes duration 7.5 (0.2–24 yrs) than those with normal albumin excretion rate 3 (0–25 yrs), p < 0.001." (PMID 17224056, 2007). "Age, male gender, duration of diabetes, spot urinary albumin: creatinine ratio, estimated glomerular filtration rate, total cholesterol (TC), high density lipoprotein cholesterol (HDL-C) and current smoking status were risk factors of CHD." (PMID 18053157, 2007).